BCL6 (BCL6 transcription repressor)
Diseases named in the same sentence as BCL6 in open-access papers (continued):
Sharing a sentence is not in itself a finding about the gene and the disease.
leukemia (continued). "In leukemia, where Treg cells display a Th2-like phenotype including expression of ST2, Tbet, and Bcl6 are repressed, and Blimp1 is increased, whereas ST2 neutralization inversely affects the Tbet, Bcl6, and Blimp1 transcription factors program." (PMID 40691440, 2025). "The balance between BACH2 and BCL6 controls the pre-B cell receptor checkpoint; however, its oncogenic effect in leukemia and its clinical relevance are not yet fully clarified." (PMID 28030830, 2017). "Importantly, BCL6 and BACH2 show antagonism during early B cell development, as well as in repertoire selection and counter-selection of premalignant clones for leukemia suppression." (PMID 28030830, 2017). "Finally, B lymphoblasts with BCR-ABL phenotype lacking BCL6 were not able to induce leukemia in immunodeficient mice." (PMID 32085659, 2020). "However, there are no reports about BCL6/BACH2 expression in leukemia patients." (PMID 28030830, 2017). "A similar pattern of regulation was previously observed for instance for the oncogene BCL6 which is non-detectable at baseline but can strikingly be upregulated upon Imatinib (IM) treatment emitting its oncogenic function by allowing leukemia cells to escape TKI-mediated cell death." (PMID 26862466, 2015).
atherosclerosis (31 papers, 2013 to 2025). A disease characterized by the build-up of fatty material and calcium deposition in the arterial wall resulting in partial or complete occlusion of the arterial lumen. "Data from mouse models reported that Bcl6 expression was reduced in the presence of mir-155 (microRNA 155) deficiency in advanced atherosclerosis, supporting its involvement in the modulation of the atherosclerotic process." (PMID 39035772, 2024). "Deficiency of the specific Tfh transcription factor Bcl6 decreased atherosclerosis, indicating that Tfh cells are pro-atherogenic [23•], presumably because they induce B-cell activation and secretion of IL-21." (PMID 37395922, 2023). "Further, recent studies have uncovered that BCL6 negatively regulates atherogenic gene expression in vivo and loss of BCL6 in bone marrow accelerates inflammation and/or cholesterol-dependent atherosclerosis." (PMID 37681868, 2023). "Deficiency of Bcl6 in bone-marrow cells of LDL receptor-deficient mice substantially promotes atherosclerosis by increasing CCL2 expression." (PMID 26001902, 2015). "Similarly, myeloid-BCL6 deficiency also robustly elevated HFD-induced vascular inflammatory disease conditions such as atherosclerosis." (PMID 37681868, 2023). "MiR-155 is upregulated in response to pro-inflammatory signals, promoting vascular inflammation and atherosclerosis by suppressing B-cell lymphoma 6 protein (Bcl6) in macrophages, thereby enhancing inflammatory responses." (PMID 40332077, 2025). "Antagomir-155 nanotherapy can reduce inflammation in atherosclerotic lesions and alleviate atherosclerosis by downregulating miR-155 and its target gene, Bcl6." (PMID 40332077, 2025). "One caveat to this atherosclerosis study was that Bcl6 is also expressed by germinal center B-cells that have a pro-atherogenic role." (PMID 37395922, 2023). "During atherosclerosis development, miR-155 begins to stimulate atherosclerosis progression through repressing Bcl6 in macrophages, suppressing the expression of eNOS, and increasing pro-inflammatory NF-κB signaling." (PMID 36555285, 2022). "The miR-155 has also been described to promote inflammatory activation of macrophages by repressing B-cell leukemia/lymphoma (BCL-6), a negative regulator of nuclear factor-kappa B (NF-κB) signaling, thus promoting atherosclerosis." (PMID 36142173, 2022). "As atherosclerosis progresses, T cells express proatherogenic Treg transcription factors, including RORγ-T (Th17), Bcl-6 (TFH), or T-bet (Th1), instead of the atheroprotective Th transcription factor FoxP3." (PMID 33613306, 2021). "miR-155 was reported to promote atherosclerosis by inhibition of BCL-6 in macrophages further highlighting that miR-155 plays a key regulatory role in atherosclerotic development which warrants further investigation." (PMID 33391256, 2020). "In this regard, cholesterol attenuates IL‐2 signaling, and induces Bcl6 expression and Tfh differentiation in the context of atherosclerosis." (PMID 33230950, 2020). "miR-155 has also been seen to promote inflammatory activation of macrophages by repressing B-cell leukemia/lymphoma (BCL) 6, a negative regulator of NF-κB signaling, thus promoting atherosclerosis." (PMID 31627295, 2019). "On the other hand, targeting of Bcl6 by miR-155 fosters atherosclerosis due to increased MCP1 level and impaired macrophage efferocytosis at the late stage in mice." (PMID 29899293, 2018). "More specifically, mRNA targets such as Bcl6, Hbp1, Mst2, and Socs1, which are reduced in atherosclerosis have been shown to play a protective role against the disease’s development." (PMID 30369883, 2018). "IL-2 and pSTAT5 are also potent inhibitors of Tfh differentiation, suggesting that cholesterol-mediated IL-2 signaling attenuation, together with increased IL-6R and Bcl6 expression, initiate Tfh differentiation in context of atherosclerosis." (PMID 29545616, 2018).
atherosclerosis (continued). "Surprisingly, nevertheless, our research revealed that BCL6 gene expression was up-regulated, which may be connected to negative feedback regulation in individuals with high levels of atherosclerosis." (PMID 38228864, 2024). "Increasing Bcl6 expression reduces inflammatory responses and limits atherosclerosis." (PMID 36299582, 2022). "Consequently, cholesterol-mediated attenuation of IL-2 signaling, along with the increased IL-6R and Bcl6 expression, initiate Tfh differentiation in the context of atherosclerosis." (PMID 33465845, 2021). "BCL6 levels are correlated with disease severity in patients with atherosclerosis." (PMID 34218797, 2021). "The stage-dependent role of miR-155 suggests that blocking the interaction between miR-155 and Bcl6 might be a potential therapeutic strategy for atherosclerosis." (PMID 29899293, 2018). "MiR-155 was reported to be upregulated in human carotid plaque, and could prompt the inflammatory response during atherosclerosis by repressing B-cell leukemia/lymphoma 6 (Bcl6) in macrophages." (PMID 28961259, 2017). "A German research team demonstrated that miRNA-155 was specifically expressed in atherosclerotic plaques and proinflammatory macrophages and promoted atherosclerosis by the mechanism of repressing target gene B-cell lymphoma 6 protein (BCL6) expression in atherosclerotic mice." (PMID 28018919, 2016). "BCL-6 could contribute to the prevention of atherosclerosis by recruiting, with a high degree of overlap, SMRT and NCoR-corepressor complexes to control the expression of inflammatory and atherogenic genes." (PMID 26162096, 2015). "In addition, we cannot exclude the role of miRNA, such as miR-155, that in macrophages was shown to repress the expression of BCL-6 in attenuating NF-κB signalling in advanced atherosclerosis." (PMID 26162096, 2015). "Additionally, silencing Bcl6 may lead to unexpected outcomes such as atherosclerosis and xanthomatous tendinitis." (PMID 40416976, 2025). "Moreover, blocking the interaction of miR-155 and its target Bcl6 maintains macrophage quiescence by suppressing CCL2 expression, which prevents the progression of atherosclerosis." (PMID 26001902, 2015). "Chronic inflammation is a hallmark of atherosclerosis, Barish GD examined the impact of the transcriptional repressor BCL6 on atherogenesis and revealed BCL6-SMRT/NCoR complexes could constrain immune responses and contribute to the prevention of atherosclerosis." (PMID 35151267, 2022).
viral infection (29 papers, 2015 to 2025). "IL‐6 deficiency results in the severe reduction of CXCR5+BCL6+ early Tfh cells in vivo within 72 hours of an acute viral infection." (PMID 34032001, 2021). "The differentiation of Tfh cells was impaired in Egr2 and Egr3 deficient mice post viral infection because of the defective expression of Bcl-6, resulting in a defective GC reaction and antibody production." (PMID 30828337, 2019). "The Egr2 and 3 transcription factors are important for the development of viral responding Tfh cells following viral infection by direct regulation of Bcl6 expression." (PMID 39568245, 2025). "Nonetheless, similar to viral infection models, Bcl6 and T-bet were co-expressed by the T cells at this early stage." (PMID 35911733, 2022). "Lineage commitment to TFH lineage has occurred on day 3 post viral infection, as detected by Bcl-6+CXCR5+ cells." (PMID 33637761, 2021). "Transcription factor TCF1 is expressed at an extremely high level in Tfh cells post-viral infection and exerts crucial roles in generation, maintenance, and effector functions of Tfh cells by repressing Prdm1 and Il2ra and promoting Bcl6 expression." (PMID 33595435, 2021). "TCF-1 directly binds to the Bcl6 transcription start site and Prdm1 5′ regulatory regions, which promotes the expression of Bcl6 and represses the expression of Blimp-1 during acute viral infection." (PMID 32766317, 2020). "Apart from the master regulator Bcl-6, a network of several other transcription factors also participates in controlling the differentiation of Tfh cells during acute viral infection." (PMID 30828337, 2019). "Propelled by the antagonism of Bcl6 and Blimp-1, activated CD4+ T cells undergo a bimodal fate decision during acute viral infection: becoming either Tfh (Bcl6+Blimp1−) cells or Th1 (Bcl6−Blimp1+) cells." (PMID 30828337, 2019). "mTORC1 was found to be essential for Tfr differentiation during viral infection by activating STAT-3 to promote the TCF-1/Bcl-6 transcriptional axis to launch the Tfr transcriptional program." (PMID 30524440, 2018). "Active de-repression of the antiviral program is largely dependent on the induction of miR-127, which, upon viral infection, potentially suppresses the expression of Bcl6 and impairs the inhibitory complex at IRF7 loci." (PMID 26728228, 2016). "This was associated with the improved symptoms of viral pneumonia, indicating that disruption of the interaction between Bcl6 and co-factors de-repressed the antiviral signaling and conveyed the protection against viral infection in vivo." (PMID 26728228, 2016). "Together, our data demonstrated a prominent and specific role of the miR-127/Bcl6/IRF7 loop in the host innate immunity against viral infection." (PMID 26728228, 2016). "Enforced expression of BCL6 in EGR2/3-deficient CD4 T cells partially restored Tfh differentiation and GC formation in response to virus infection." (PMID 25979336, 2015). "Following virus infection, most of the Tfh cells in wild type mice expressed BCL6, whereas BCL6 expression was defective in the few remaining Tfh cells in CD2-Egr2−/−Egr3−/− mice." (PMID 25979336, 2015). "While Bcl6 also displayed a distinct motif enrichment pattern, its role appears more prominent in the D8MPEChi population compared to Tcf7 and Lef1, this is consistent with recent finding that Bcl6 is required for the generation of CD8+ memory precursors upon acute viral infection." (PMID 39804040, 2025). "Although Bcl6 has been recognized to be the lineage-determining transcription factor for Tfh cells in viral infection as early as 2009, it has only recently been determined that CD4+ T cell-intrinsic Bcl6 signalling is also required for the induction of Tfh responses in malaria." (PMID 36845571, 2021). "Indeed, GC Tfh cells induced following viral infections, where Th1 inflammatory responses predominate, express Bcl-6, Tbx21, IFN-γ, and IL-21, consistent with the induction of Th1-type Tfh cells." (PMID 31827000, 2020).
viral infection (continued). "The antagonism between STAT1 and STAT3 seems to be cell type-specific or specific to a certain gene locus, as a cooperation between STAT1 and STAT3 downstream of IL-6 has been described for optimal Bcl6 induction and Tfh differentiation in response to viral infections." (PMID 31998303, 2019). "It is known that viral infections induce both Th1 and Tfh cells under the transcriptional control of T-bet and Bcl6, respectively; however, the particular cytokine milieu may also shape their differentiation pathways." (PMID 31455769, 2019). "In addition, at the late stage of chronic viral infection, IL-6 derived from activated follicular DCs is crucial for maintenance of Tfh cell by upregulation of Bcl6 and viral control." (PMID 30158933, 2018). "In addition, specific ablation of either Tcf1 or Ezh2 in mature CD4+ T cells impaired TFH differentiation, and targeting both proteins almost completely abrogated the TFH cell formation and Bcl6 induction elicited by viral infection." (PMID 30575739, 2018). "Interestingly after acute viral infection, T-bet is co-expressed with Bcl6 in Tfh cells and is required alongside STAT4 to coordinate IL-21 and IFN-γ production in Tfh cells and for promotion of the GC response." (PMID 30158933, 2018). "In contrast, IRF7 level was markedly repressed by Bcl6 overexpression and boosted by Bcl6 deletion in macrophages during viral infection, suggesting that selective regulation of IRF7 expression may contribute to Bcl6-mediated RIG-I signaling modulation." (PMID 26728228, 2016). "As summarized in this review, Tfh cell-related transcription factors including Bcl6, IRF4, STAT1/STAT4/STAT5, T-bet, TCF-1, LEF-1, TOX2, Bach2, FOXP1, and KLF2 are all involved in the virus infection." (PMID 32766317, 2020). "IL-6 promotes Tfh function and alleviates chronic viral infection in mice, due in part to inhibiting TGF-ß-dependent generation of regulatory T cells and increased Bcl-6 expression in Tfh." (PMID 30524440, 2018). "STAT1 is an important transcription factor to promote IL-6-dependent Bcl6 induction and TFH differentiation during the DC priming stage of acute viral infections." (PMID 30057920, 2018). "Our data also indicated for the first time in the context of viral infection that Tfh cells express KLF2 and Foxo1, which are inhibitory transcriptional factors responsible for arresting CXCR5 and Bcl-6 expression." (PMID 26640894, 2015). "Apart from differentiation, BCL6 is also essential for the maintenance of Tfh cells in vivo, as temporal ablation of BCL6 by tamoxifen (CD4-CreERT2) induces the transdifferentiation of established Tfh cells into TBX21+ Th1 cells during acute viral infection." (PMID 34349770, 2021). "In response to viral infection, GC B cells (e.g., Ki67+, Bcl6+) were detected in the mediastinal LNs of WT mice, but not in TCRα-deficient mice, demonstrating that T cells are essential for GC formation in this organ as well." (PMID 32049020, 2020). "In the absence of EGR2 and -3, the expression of BCL6 in Tfh cells is defective, leading to impaired differentiation of Tfh cells, resulting in a failure to form GCs following virus infection and defects in production of antiviral antibodies." (PMID 25979336, 2015).
COVID-19 (28 papers, 2020 to 2025). A disease caused by infection with severe acute respiratory syndrome coronavirus 2. "This aligns with previous findings showing that TNFA from macrophages is a key factor in the loss of GC Bcl6 expression in COVID-19 LNs." (PMID 40924502, 2025). "It is known that GCs can be lost in lymph nodes and spleen in acute COVID-19, and this has been linked to diminishing of BCL6+ B and T cells in these tissues and blood." (PMID 35251032, 2022). "Expression of the GC-associated BCL6 transcription factor was reduced in T and B cells of follicular area from COVID-19 samples compared to those from controls." (PMID 35251032, 2022). "BCL6 has low activity in severe and moderate COVID-19 patients; its loss implies hyper-proliferation, followed by the expression of STAT3 to secrete IL-6, contributing to the cytokine storm in severe COVID-19 patients." (PMID 34603282, 2021). "The severity of COVID-19 infection might be also associated with the function of Tfh1 cells, since it has recently been shown that in active severe COVID-19 patients there is a loss of BCL6+ Tfh cells and GCs, together with an increase in TBET+ Th1 cells." (PMID 36254574, 2022). "Our findings could be explained by the recent report that found loss of Bcl6-expressing T follicular cells (Tfh) and germinal centers (GC) in autopsy of respiratory tissues (including lymph nodes) from deceased COVID-19 patients." (PMID 33619281, 2021). "We stratified COVID-19 LD-LNs into 3 distinct groups based on Bcl6 expression profile to assess follicular immune reactivity." (PMID 40924502, 2025). "Altogether, our data indicate that the expression of Bcl6 in LD-LNs from COVID-19 autopsies reflects a spectrum of follicular immune reactivity." (PMID 40924502, 2025). "In the present study a depletion of BCL6- expressing B and T cells in PP was also observed in COVID-19." (PMID 35251032, 2022). "Among the upregulated genes in post-COVID-19 monocytes, we still found the acute-COVID-19 upregulated BCL6, AREG and IL-10." (PMID 34572439, 2021). "Acute COVID-19 monocytes transcriptome showed upregulation of anti-inflammatory tissue repair genes such as BCL6, AREG and IL-10 and increased accessibility of chromatin." (PMID 34572439, 2021). "A recent study showed that in severe COVID-19 patients, within 10 days of the onset of respiratory symptoms, splenic and lymph node germinal centers (GCs) and B cell lymphoma 6 (Bcl-6+) expressing B cells are markedly diminished." (PMID 33302366, 2020). "In line with previous studies, the absence of Bcl6 expression in COVID-19 hilar LNs has been linked to TNFA overexpression, which impairs Tfh differentiation." (PMID 40924502, 2025). "This suggests that Bcl6-dependent GC formation in COVID-19 could be influenced by the local availability of antigens or local inflammatory signals." (PMID 40924502, 2025). "Similarly, for COVID-19, BCL6, PRR11, and GAS2L1 showed significant positive correlations with hypoxia, cholesterol homeostasis, xenobiotic metabolism, and glycolysis, and negative correlations with oxidative phosphorylation." (PMID 39965013, 2025). "ACE (AUC: 0.923), CYP1A1 (AUC: 0.902), EME1 (AUC: 0.977), CD52 (AUC: 0.970), MYBL2 (AUC: 0.995), CDC25A (AUC: 0.998), BCL6 (AUC: 0.966) and CD3D (AUC: 0.955) showed relatively good diagnostic efficiency in distinguishing COVID-19 patients from healthy controls." (PMID 38978778, 2024). "Interestingly, in the context of the COVID-19 pandemic, it has been observed that Bcl-6+ GC B cells and Bcl-6+ TFH cells are markedly diminished in SARS-CoV-2 infection." (PMID 36591222, 2022). "Delayed humoral immune evolution may be explained by defective Bcl-6-expressing T follicular helper cell evolution in severe/fatal COVID-19 leading to delayed and defective humoral immune evolution." (PMID 35762593, 2022). "The percentages of T cells that were BCL6+PD1+ were significantly reduced in COVID-19 samples." (PMID 35251032, 2022).